RNU6-23P (RNA, U6 small nuclear 23, pseudogene)
Synonyms: RNU6-23
Gene: Small nuclear RNA gene on chromosome 16 (70,445,293 to 70,445,399, reverse strand). Ensembl gene ENSG00000200153.
Homologues: Orthologues: chimpanzee U6 (98% identical), dog U6 (93% identical), macaque U6 (93% identical), rabbit U6 (93% identical), pig U6 (93% identical), rat U6 (90% identical). Paralogues in human: RNU6-11P (94% identical), RNU6-37P (94% identical), RNU6-1 (93% identical), RNU6-1175P (93% identical), RNU6-2 (93% identical), RNU6-3P (93% identical), RNU6-43P (93% identical), RNU6-4P (93% identical), RNU6-5P (93% identical), RNU6-6P (93% identical), RNU6-7 (93% identical), RNU6-8 (93% identical), and 1286 more.